PODXL2 (podocalyxin like 2)
Description:
Acts as a ligand for vascular selectins. Mediates rapid rolling of leukocytes over vascular surfaces through high affinity divalent cation-dependent interactions with E-, P- and L-selectins.
Synonyms: PODLX2; endoglycan; EG
Tractability: Antibody: its Gene Ontology location is reachable by antibodies, with high confidence; UniProt predicts a signal peptide or a membrane-spanning region. PROTAC: ubiquitination databases record sites on it; its protein half-life has been measured.
Gene: Protein-coding gene on chromosome 3 (127,629,143 to 127,672,810, forward strand). Ensembl gene ENSG00000114631.
Subcellular location: Membrane
Subcellular location (Human Protein Atlas): Golgi apparatus; Vesicles
Pathways (Reactome):
Metabolism: Cytosolic sulfonation of small molecules
Gene Ontology:
Molecular function: protein binding; glycosaminoglycan binding
Biological process: leukocyte tethering or rolling
Cellular component: Golgi lumen; plasma membrane; membrane
Genetic constraint (gnomAD): Loss-of-function variants: 15 observed, 44.17 expected, observed/expected ratio (o/e) 0.34, 90% interval 0.23 to 0.52. The upper end of that interval is the gene's LOEUF score, 0.52, which puts it in group 2 of 6, group 1 being the genes least tolerant of losing a copy. Missense variants: 634 observed, 704.06 expected, observed/expected ratio (o/e) 0.9, 90% interval 0.84 to 0.96. Synonymous variants: 292 observed, 280.73 expected, observed/expected ratio (o/e) 1.04, 90% interval 0.94 to 1.15.
Homologues: Orthologues: chimpanzee PODXL2 (99% identical), macaque PODXL2 (97% identical), dog PODXL2 (83% identical), mouse Podxl2 (77% identical), rat Podxl2 (77% identical), guinea pig PODXL2 (76% identical), rabbit PODXL2 (74% identical), pig PODXL2 (73% identical), tropical clawed frog podxl2 (35% identical).
Diseases named in the same sentence as PODXL2 in open-access papers:
PODXL2 is named in the same sentence as 12 diseases in open-access papers, as found by Europe PMC text mining. Sharing a sentence is not in itself a finding about the gene and the disease. The quoted sentences say what the papers report.
breast carcinoma (3 papers, 2020 to 2022). "In BT474 breast cancer cells, knockdown of PODXL2 slightly suppressed tumor cell migration and reduced expression of cancer stem cell markers through the Rac family small GTPase 1 pathway." (PMID 34208313, 2021). "Knockdown of PODXL2 in breast cancer cell lines inhibited long-term cell proliferation in a colony-formation assay and suppressed migration in a wound-healing assay." (PMID 32669966, 2020). "The present study identified that mRNA and protein levels of PODXL2 were highly expressed in breast carcinoma, which resulted in poor prognoses of breast cancer patients." (PMID 32669966, 2020). "According to the heat map, we chose four kinds of breast cancer cell lines with different expression levels of PODXL2, including BT474, BT483, MCF7, and MDA-MB-231 cells." (PMID 32669966, 2020). "The Oncomine and cBioPortal databases collect mRNA expression from several datasets of breast cancer, and genes coexpressed with PODXL2, these coexpressed genes were uploaded to MetaCore to analyze associated pathways." (PMID 32669966, 2020). "The bioinformatics analysis confirmed that high PODXL2 expression was correlated with poor prognoses of breast cancer patients." (PMID 32669966, 2020). "High expression of PODXL2 mRNA was correlated with poor disease-free survival of breast cancer patients in the Kaplan-Meier Plotter." (PMID 32669966, 2020). "Through the bioinformatics analyzed from Symmans and Desmedt breast cancer datasets revealed that patients with metastatic events had higher PODXL2 expression levels." (PMID 32669966, 2020). "Our bioinformatics analysis and in vitro experiments revealed that PODXL2 plays an oncogenic role in breast cancer development via the Rac1 pathway." (PMID 32669966, 2020). "The bioinformatics analysis revealed that PODXL2 overexpression was correlated with poor survival of breast cancer patients, suggesting an oncogenic role of PODXL2 in breast carcinoma." (PMID 32669966, 2020). "PODXL2 was implied to have a crucial role in breast cancer because it is a type-I transmembrane sialomucin." (PMID 32669966, 2020). "Our results confirmed that increased PODXL2 expression should play an important role in breast cancer." (PMID 32669966, 2020). "PODXL2 was overexpressed in six of 43 studies of breast cancer, primary and metastatic breast cancer, mRNA expression, and IHC staining of proteins." (PMID 32669966, 2020). "PODXL2 is thought to play a crucial role in breast cancer, because PODXL2 is a transmembrane mucin with a PDZ domain that interacts with intracellular signal transduction." (PMID 32669966, 2020). "PODXL2 mRNA expression increased from stage 0 to stage IV breast cancer and the value from stage 0 (n = 253, mean = -0.600 ± 0.895), stage II (n = 205, mean = -0.251 ± 0.907), stage III (n = 77, mean = -0.159 ± 0.882), elevated till stage IV (n = 12, mean = -0.079 ± 0.853)." (PMID 32669966, 2020). "PODXL2 mRNA expression in breast cancers was upregulated in the METABRIC database." (PMID 32669966, 2020). "We hypothesized that PODXL2 plays a similar role as PODXL in breast cancer, and increased PODXL2 expression in breast cancer promotes tumor progression." (PMID 32669966, 2020). "The MetaCore pathway analysis suggested that “signal transduction: angiotensin II/angiotensin II receptor type 1 (AGTR1) signaling via Ras homolog family member A (RhoA) and c-Jun N-terminal kinase (JNK)” had a high correlation with breast cancers exhibiting PODXL2 expression." (PMID 32669966, 2020). "Our results demonstrated that PODXL2 mRNA and protein were highly expressed in breast cancer." (PMID 32669966, 2020). "In summary, PODXL2 plays a significant role in breast cancer." (PMID 32669966, 2020). "In the present study, PODXL2 expression was detected in breast cancer tissues." (PMID 32669966, 2020). "ATGR1/RhoA/JNK signaling was correlated with PODXL2 expression in breast cancer." (PMID 32669966, 2020).
breast carcinoma (continued). "High PODXL2 expression was correlated with poor disease-free survival of breast cancer patients." (PMID 32669966, 2020). "Our results suggested that increased PODXL2 expression could serve as a biomarker and a therapeutic target in patients with breast cancer." (PMID 32669966, 2020). "We suggest that increased PODXL2 expression could be used as a biomarker in patients with breast cancer." (PMID 32669966, 2020). "The present study confirmed the function of PODXL2 in breast cancer." (PMID 32669966, 2020). "The inferential network implied the function of PODXL2 in breast cancer." (PMID 32669966, 2020). "Collectively, our present study demonstrated that PODXL2 plays a crucial role in cancer development and could serve as a potential prognostic biomarker in breast cancer patients." (PMID 32669966, 2020). "Increased PODXL2 expression is a predictor of recurrence in patients with breast cancer, and PODXL2 may provide a potential target for therapy." (PMID 32669966, 2020). "PODXL2 also had high expression in breast cancers from the TCGA dataset." (PMID 32669966, 2020). "In addition to bioinformatics predictions, we also performed an in vitro study with a breast cancer cell line to confirm the function of PODXL2." (PMID 32669966, 2020). "Inhibition of colony formation in ITGB6-ko iCCA cells in the present study might also be induced by reduced expression of PODXL2, because PODXL2 might be necessary for the maintenance of clonogenic potential in CCA cells as indicated in breast cancer cells." (PMID 34208313, 2021).
lung adenocarcinoma (2 papers, 2020 to 2021). A carcinoma that arises from the lung and is characterized by the presence of malignant glandular epithelial cells. "(D, E) Log ratios of (D) PODXL2 and (E) STAG3 expression in MGA altered vs. WT lung adenocarcinoma patients." (PMID 34236315, 2021).
glioma (1 paper, 2019). A benign or malignant brain and spinal cord tumor that arises from glial cells (astrocytes, oligodendrocytes, ependymal cells). "However, little is known about the role of ACVR1B and PODXL2 on gliomas." (PMID 31118022, 2019).
invasive ductal breast carcinoma (1 paper, 2020). The most common type of invasive breast carcinoma, accounting for approximately 70% of breast carcinomas. "Empirical validation of bioinformatics predictions was conducted utilizing the short hairpin (sh)-RNA silencing method for PODXL2 in the BT474 invasive ductal breast carcinoma cell line." (PMID 32669966, 2020).
lung carcinoma (1 paper, 2021). "Importantly, we observed that four of the five genes (STAG3, PODXL2, NHLRC1, and ZCWPW1) identified from our analysis in lung cancer models were significantly upregulated upon loss of MGA." (PMID 34236315, 2021). "In order to study the importance of these genes in lung cancer cells, we performed siRNA knockdowns of STAG3 and PODXL2 in control and sgMGA cells." (PMID 34236315, 2021).
prostate carcinoma (1 paper, 2020). A carcinoma that arises from epithelial cells of the prostate gland. "Podocalyxin (including PODXL1, PODXL2 and PODXL3) induction resulted in altered migration and invasion, increased MMP expression with increased MAPK and PI3K activity through forming a complex with Ezrin protein, in breast and prostate cancer." (PMID 32998690, 2020).
cancer (5 papers, 2010 to 2022). A tumor composed of atypical neoplastic, often pleomorphic cells that invade other tissues. "High PODXL2 expression in the Desmedt dataset was associated with cancer recurrence at 1 year post-therapy." (PMID 32669966, 2020). "STRING software selected the most closely associated genes with PODXL2 in cancer." (PMID 32669966, 2020). "Rac1 interacts with Akt1 to increase cancer cell stemness downstream of PODXL2 and also enhance cell migration through the Axl/Rac1/Akt1-mediated axis." (PMID 35456223, 2022). "The analyses showed that the mRNA level of PODXL2 was overexpressed in 8 of 20 types of cancers compared to normal tissues." (PMID 32669966, 2020). "All other 35 analyses showed fold change of PODXL2 larger than 0, which meant cancer tissue have higher expression of PODXL2 than normal tissue." (PMID 32669966, 2020). "All these bioinformatics tools are useful for predicting interactions and functions of PODXL2 in cancers." (PMID 32669966, 2020). "The mean ± SD of difference of PODXL2 between cancer and normal was 1.080 ± 2.524 with p-value 3.148E-18." (PMID 32669966, 2020). "The mean difference and standard deviation (mean ± SD of difference) of PODXL2 between cancer and normal was 0.994 ± 3.010 with p-value 2.826E-40." (PMID 32669966, 2020). "In the present study, we explored the function of PODXL2 in cancer and analyzed the influence of expression of the PODXL2 protein on clinical outcomes of cancer patients." (PMID 32669966, 2020). "We analyzed mRNA expression levels of PODXL2 in 20 common cancers from the Oncomine database." (PMID 32669966, 2020). "In addition, knockdown of PODXL2 reduced expression levels of cancer stem cell (CSC) markers, including Oct-4 and Nanog, and the breast CSC marker aldehyde dehydrogenase 1 (ALDH1)." (PMID 32669966, 2020). "However, the role of PODXL2 in cancer has been less fully explored." (PMID 32669966, 2020). "The role of PODXL2 in cancer is not yet known, and no interacting partners or regulators have been identified." (PMID 34208313, 2021). "However, the correlation between PODXL2 and cancer is not yet well studied." (PMID 32669966, 2020).
tumor (5 papers, 2020 to 2023). "Furthermore, PODXL2 is suggested to be involved in tumor metastasis and to play a role in breast CSCs." (PMID 32669966, 2020). "The results showed that compared with HSKMC, PODXL2, LRRC17, GABRA3, SCUBE3, and RFLNB were highly expressed in tumor cells, while IGHG2 and HLF were low expressed." (PMID 36155774, 2022). "So far, no studies have shown that these seven genes (IGHG2, PODXL2, LRRC17, GABRA3, SCUBE3, HLF and RFLNB) are directly related to pyroptosis in tumor cells." (PMID 36155774, 2022).
PODXL2 also shares sentences with these, for which no sentence is quoted: cholangiocarcinoma (1 paper); eosinophilia (1); intrahepatic cholangiocarcinoma (1); sarcoma (1).